SLC9A3 (solute carrier family 9 member A3)
Diseases named in the same sentence as SLC9A3 in open-access papers:
SLC9A3 is named in the same sentence as 128 diseases in open-access papers, as found by Europe PMC text mining. Sharing a sentence is not in itself a finding about the gene and the disease. The quoted sentences say what the papers report.
Hypertension (39 papers, 2012 to 2025). The presence of chronic increased pressure in the systemic arterial system. "SLC9A3 is a potential drug target for hypertension by reducing salt uptake in the gut21." (PMID 38062110, 2023). "Overall, the sex-specific effects seen in PAH, SLC9A3 and CYP2E1 genes likely play an important role in sex-specific responses to prenatal stress, and a comprehensive study needs to be undertaken to examine their role in the programming of hypertension." (PMID 31483805, 2019).
colitis (20 papers, 2008 to 2023). Inflammation of the colon. "Indeed, SLC9A3 has been found downregulated in patients with ulcerative colitis (colon inflammation) and its loss of function has been linked to diarrhoea disorders." (PMID 34151400, 2021). "In spite of these inconsistencies between humans and mice, an important interaction in mammals between mucosal SLC9A3 and commensal bacteria appears to exist, which may be relevant for modulating colitis susceptibility." (PMID 27006956, 2016). "Slc9a3 knockout mice show increased bacterial penetration, inflammation, and spontaneous development of colitis, in addition to reduced colonic microbial diversity." (PMID 28170448, 2017). "This gene has altered expression in the colonic mucosa of adult IBD patients, and SLC9A3 knockout mice develop colitis." (PMID 27006956, 2016). "In adoptive T cell transfer colitis model, Slc9a3 status was the most significant determinant of gut microbial community." (PMID 27050757, 2016).
adenoma (19 papers, 2013 to 2026). A neoplasm arising from the epithelium. "This is facilitated by the coupled activity of the Na+/H+ exchanger NHE3 (sodium: proton exchanger-3 encoded by the SLC9A3 gene) and the Cl−/HCO3− exchanger DRA (Downregulated in Adenoma encoded by the SLC26A3 gene), with DRA predominantly expressed in the distal colon." (PMID 41009702, 2025). "Coupled NaCl absorption occurs via the dual operation of Na:H (NHE3; Slc9a3) and Cl:HCO3 (Down Regulated in Adenoma (DRA; Slc26a3) or Putative Anion Transporter 1 (PAT1; Slc26a6)) exchange." (PMID 30126234, 2018). "For example, Slc9a3 contains a hypermethylated DMR in the promoter, and is strongly activated in adenoma." (PMID 23408899, 2013). "Coupled NaCl absorption occurs via the functional coupling of villus cell brush border membrane (BBM) Na:H exchange (NHE3, sodium–hydrogen exchanger 3/SLC9A3) and Cl:HCO3 exchange (DRA, downregulated in adenoma/SLC26A3 and PAT1, putative anion transporter-1/SLC26A6)." (PMID 39456989, 2024).
diabetes (11 papers, 2021 to 2025). "SLC9A3's polymorphism rs17563161 was associated with MI in two studies in addition to PI and diabetes mellitus, similar to deletions in the GSTT1 gene." (PMID 40225935, 2024). "GLP-1 analogs stimulate natriuresis at physiological levels by inhibiting sodium reabsorption via decreased activity of sodium–hydrogen exchanger 3 (NHE3) or solute carrier family 9 member 3 (SLC9A3) in the proximal tubules, resulting in decreased blood pressure in patients with diabetes." (PMID 37375783, 2023).
ulcerative colitis (10 papers, 2012 to 2025). An inflammatory bowel disease involving the mucosal surface of the large intestine and rectum. "SLC9A3 encodes Na(+)/H(+) exchanger (NHE3), which is down-regulated in patients with ulcerative colitis." (PMID 27855662, 2016). "Moreover, genome-wide association studies (GWASs) in IBD patients have shown a strong association between ulcerative colitis and the SLC9A3 locus." (PMID 40649913, 2025). "The polymorphism rs11739663, which is located close to SLC9A3, is a single-nucleotide polymorphism (SNP) associated with ulcerative colitis, suggesting a potential explanation for the association between SLC9A3 mutations and the development of inflammatory bowel disease later in life." (PMID 36422736, 2023). "The expression of Slc9a3 is downregulated in ulcerative colitis patients and its expression is related with the degree of acute inflammation in the colon." (PMID 28170448, 2017).
cystic fibrosis (8 papers, 2019 to 2025). Autosomal recessive disorder caused by pathogenic variants in the CFTR gene (cystic fibrosis transmembrane conductance regulator), which encodes a chloride and bicarbonate channel expressed in epithelial cells, and follow the diagnosis criteria. "This is, however, due to the fact that SLC9A3 is also a cystic fibrosis modifier gene, SLC4A1 is also associated with spherocytosis, and SLC6A19 also causes Hartnup disease, all of which are comparatively frequent conditions." (PMID 35456490, 2022). "Loss of an SLC9A3 allele was also recently reported to suppress the hyperproliferation of goblet cells in the intestine of mice with cystic fibrosis." (PMID 30956978, 2019). "Solute carrier family 9 member A3 (SLC9A3) mutations cause Congenital Sodium Diarrhea (CSD) and cystic fibrosis 62-64." (PMID 40860157, 2025). "Another role of SLC9A3 as an important interacting partner or modifier of the cystic fibrosis transmembrane conductance regulator (CFTR), a gene of which mutations are causative for cystic fibrosis, has been described recently." (PMID 35239655, 2022). "The interaction between SLC9A3 and CFTR modifies the severity of cystic fibrosis." (PMID 30956978, 2019).
Diarrhea (5 papers, 2023 to 2025). Abnormally increased frequency (usually defined as three or more) loose or watery bowel movements a day. "SLC26A3 interacts with several ion transporters linked to intestinal inflammation, such as cystic fibrosis transmembrane conductance regulator (CFTR) and solute carrier family 9 member 3 (SLC9A3) causing congenital sodium diarrhea." (PMID 39992989, 2025). "In the ileum and proximal colon, absorption of sodium chloride occurs predominantly via the coupled action of SLC26A3 and SLC9A3, which is disrupted in congenital sodium diarrhea (CSD) and linked to IBD risk." (PMID 39992989, 2025). "Similarly, congenital sodium diarrhea is linked to a defect in SLC9A3, which encodes the Na+/H+ antiporter 3 (NHE3)." (PMID 40649913, 2025). "CEAS/CNSU caused by SLCO2A1 defects, as well as congenital/familial diarrhea associated with SLC26A1, SLC9A3, and GUCY2C mutations, were the most prevalent monogenic disorders in patients with LO-mIBD, significantly more common than in those with IO-mIBD (p < 0.001)." (PMID 40474095, 2025).
chronic kidney disease (4 papers, 2021 to 2025). Impairment of the renal function secondary to chronic kidney damage persisting for three or more months. "The SLC9A3 inhibitor tenapanor for the treatment of hyperphosphatemia in patients with constipated IBS and dialysis chronic kidney disease or end-stage renal disease." (PMID 39850557, 2024).
intestinal obstruction (4 papers, 2012 to 2022). Blockage of the normal flow of the intestinal contents within the bowel. "Knockout of SLC9A3 alleviated intestinal obstruction commonly observed in the mouse model of CF25, and a subsequent hypothesis-driven genome-wide association study identified SLC9A3 as a modifier of neonatal intestinal obstruction in humans with CF26." (PMID 26417704, 2015).
Obesity (4 papers, 2014 to 2026). Accumulation of substantial excess body fat. "From the known functions of these genes, GNAL, HELIOS, and SOX5 are directly related to adipose tissue metabolism or obesity, while SLC9A3, SPOCK3, ANXA10, MYLK, and VSNL1 may be indirectly related." (PMID 24962627, 2014). "This raises the question as to which of the remaining 7/11 genes (LBP, RXRB, CPLX1, GLAK2, CSTL1, SLC9A3, CA12) may also have a role in obesity." (PMID 25651499, 2015).
Azoospermia (3 papers, 2017 to 2021). Absence of any measurable level of sperm,whereby spermatozoa cannot be observed even after centrifugation of the semen pellet. "Our previous research showed that SLC9A3 deficiency causes obstructive azoospermia, degrades the epithelium of the reproductive tract, and drastically suppresses CFTR expression." (PMID 30956978, 2019). "We suggest that the obstructed azoospermia-like phenotypes in Slc9a3-/- mice were attributable to both SLC9A3 deficiency and reduced CFTR expression." (PMID 28384194, 2017). "In addition to the previously reported role of SLC9A3 in the digestive system and efferent ductules, we now report that the SLC9A3 deficiency causes obstructive azoospermia and impairs the epithelial structure of the reproductive tract." (PMID 28384194, 2017). "Our data indicated reduced CFTR levels and obstructed azoospermia-like phenotypes in the reproductive ducts of Slc9a3-/- mice." (PMID 28384194, 2017). "Instead, deficiency in solute carrier family 9 sodium/hydrogen exchanger isoform 3 (SLC9A3) may play a role by generating obstructive azoospermia and degraded epithelial structure in the reproductive tract." (PMID 30956978, 2019). "Additionally, Slc9a3−/− mice present obstructed azoospermia-like phenotypes possibly attributable to lower CFTR expression, as observed in Cftr-knockout mice." (PMID 30956978, 2019). "This may be the one of the main reasons for testicular atrophy and obstructed azoospermia in Slc9a3-/- mice." (PMID 28384194, 2017). "Furthermore, Slc9a3-/- mice developed obstructive azoospermia because of abnormal abundant secretions and calcification in the lumen of the reproductive tract." (PMID 28384194, 2017). "We found that Slc9a3-/- mice displayed obstructed azoospermia-like phenotypes, which may be partially contributed to by decreased CFTR expression, similar to that observed in knockout (cf/cf) Cftr mice." (PMID 28384194, 2017).
Infertility (3 papers, 2017 to 2021). "Evaluating the causes of reduced CFTR expression and infertility in Slc9a3-/- males first requires the precise localization of SLC9A3." (PMID 28384194, 2017). "To determine the effect of SLC9A3 deficiency on infertility, we first analyzed testicular sections of WT and Slc9a3-/- mice of various ages to determine the course of progressive changes." (PMID 28384194, 2017). "SLC9A3 is a Na+/H+ exchanger, and depleted Slc9a3 in male mice causes infertility due to the abnormal dilated lumen of the rete testis and efferent ductules." (PMID 28384194, 2017). "Loss of only Slc9a1 or Slc9a3 in male mice induces infertility." (PMID 28384194, 2017). "In our results, Slc9a3-/- mice were completely infertile compared with age-matched WT and heterozygous mice." (PMID 28384194, 2017). "We suggest that the interplay between SLC9A3 and CFTR is responsible for CF-related infertility." (PMID 28384194, 2017).
male infertility (2 papers, 2017 to 2023). The inability of the male to effect fertilization of an ovum after a specified period of unprotected intercourse. "Third, Slc9a3 KO causes male infertility and reveals the abnormal dilated lumen of the rete testis and efferent ductules." (PMID 29286340, 2017).
Meconium ileus (2 papers, 2015 to 2017). Obstruction of the intestine due to abnormally thick meconium. "Genome-wide association studies have indicated that genetic variants of SLC6A14, SLC26A9, and SLC9A3 in patients with CF (n = 3,763) increased susceptibility to early meconium ileus." (PMID 28384194, 2017).
schizophrenia (2 papers, 2018 to 2021). A major psychotic disorder characterized by abnormalities in the perception or expression of reality. "Currently, there are novel drugs being developed targeting SLC9A3 that could be of interest for the field of schizophrenia." (PMID 29559890, 2018).
type 1 diabetes (2 papers, 2022 to 2023). "Na+/H+ exchanger 3 (NHE3, SLC9A3) is the major Na+ absorptive mechanism in the intestine and our previous study has demonstrated that decreased NHE3 contributes to diarrhea associated with type 1 diabetes." (PMID 35444557, 2022).
allergic asthma (1 paper, 2019). A asthma with a basis in a pathological type I hypersensitivity reaction. "Namely, for environment IgE sensitization (METTL1), for allergic asthma (NTRK1), and several for FeNO (MAP3K14, NTRK1, FBXL7, PCSK6, SLC9A3, CDH26, CAPN14, and MAP3K14)." (PMID 31300640, 2019).
asthma (1 paper, 2024). "The validated hyper-methylated co-methylated CpG site annotated to SLC9A3 is part of our asthma-risk predictive model." (PMID 38245772, 2024). "Notably, our findings showed that expression level of SLC9A3 was associated with DNA methylation changes and mediated methylation effect on asthma severity and lung function association." (PMID 38245772, 2024). "We identified several significant mediation genes including INAGL1, SERPINE1, TLR5, SLC9A3 and CD9 for asthma severity and INAGL1, TLR5, CD9 for FEV1, suggesting potential regulation effect of DNAm on gene expression in asthma." (PMID 38245772, 2024).
gastroesophageal reflux (1 paper, 2019). "Importantly, an increase in SLC9A3 expression has been correlated with the severity of gastroesophageal reflux disease, which is a major risk factor for BE." (PMID 31891614, 2019).
lung adenocarcinoma (1 paper, 2015). A carcinoma that arises from the lung and is characterized by the presence of malignant glandular epithelial cells. "The genes CEP72, BRD9, TRIP13, SLC9A3, SDHA, SLC6A19 and PDCD6 did not have any predictive role in lung adenocarcinoma prognosis." (PMID 26497366, 2015).
nephrolithiasis (1 paper, 2022). The presence of a calculus in the pelvis of the kidney; this is most often composed of mineral salts and proteins. "For example, for nephrolithiasis (PanelApp panel 149), SLC9A3, SLC4A1, and SLC6A19 appear on the top of the gene list." (PMID 35456490, 2022).
Polyuria (1 paper, 2022). An increased rate of urine production. "Indeed, we recently demonstrated that Epac1–/– and Epac2–/– mice developed polyuria and impaired urinary concentration ability in response to water deprivation driven, in part, by decreased NHE-3 (SLC9A3) expression in the proximal tubule." (PMID 34914636, 2022).
sarcoma (1 paper, 2019). A usually aggressive malignant neoplasm of the soft tissue or bone.
sterility (1 paper, 2017). "Therefore, we evaluated whether CFTR expression in Slc9a3-/- mice was reduced and contributed to the sterility." (PMID 28384194, 2017).
Testicular atrophy (1 paper, 2017). Wasting (atrophy) of the testicle (the male gonad) manifested by a decrease in size and potentially by a loss of fertility. "Slc9a3-/- males also showed testicular atrophy, calcification in the efferent ducts, and impaired cytoarchitectures of the epithelium of the excurrent ducts." (PMID 28384194, 2017).
infection (10 papers, 2008 to 2025). The state of being infected such as from the introduction of a foreign agent such as serum, vaccine, antigenic substance or organism. "Single nucleotide polymorphisms in SLC9A3 in children with CF are significantly associated with two clinical manifestations, the early infection of Pseudomonas aeruginosa and worsened pulmonary function." (PMID 28384194, 2017).
cancer (7 papers, 2019 to 2025). A tumor composed of atypical neoplastic, often pleomorphic cells that invade other tissues. "Remarkably, the TCGA database indicates that both FBXW7 and SLC9A3 are commonly co-mutated with KRAS in human cancers." (PMID 31748650, 2019). "Therefore, in future studies, it would be interesting to test in mice if mutations in Kras and Slc9a3 promote cancer development in tissues where these genes are frequently found co-mutated in human cancers." (PMID 31748650, 2019). "Moreover, SLC9A3 is found co-mutated with KRAS in human cancers in the TCGA database." (PMID 31748650, 2019). "While the impact of hypomethylation at cg18447419 on the action of AHR-mediated RhoA/Rac1 signaling is unknown, this CpG and SLC9A3 should be considered in future candidate analyses given the known interaction between this pathway and dioxin and its potential role in diseases like cancer." (PMID 33849548, 2021). "The bar plot generated by GEPIA2 clearly showed that the expressions of SLC9A2, SLC9A3, and SLC9A9 in COAD tissues were obviously lower than those in normal tissues, but SLC9A5 and SLC9A7 in cancer were distinctly higher than those in normal tissues." (PMID 34759967, 2021). "Other less or noncorrelatedpathways were also found, such as defective SLC9A3 causes histiocytosis-lymphadenopathyplus syndrome, linolenic acid metabolism affected by SARS-CoV-2, modifiednucleosides derived from rRNA as urinary cancer markers, and betaureidopropionase deficiency." (PMID 41179176, 2025).
tumor (5 papers, 2007 to 2022). "Similarly, with a sample size of 5 mice, we cannot exclude the possibility that Slc9a3 is a weak tumor suppressor in the in vivo electroporation assay that may be sufficient to drive tumorigenesis." (PMID 31748650, 2019). "Colony formation in soft agar and tumor growth in nude mice allografts were only detected in MEF-LoxP-KC cells transduced with lentivirus expressing sgRNA targeting either p19Arf, Fbxw7 or Slc9a3." (PMID 31748650, 2019).
SLC9A3 also shares sentences with these, for which no sentence is quoted: heart failure (8 papers); irritable bowel syndrome (7); inflammatory bowel disease (6); diabetic kidney disease (5); Sepsis (5); acute kidney injury (4); Constipation (4); Hyperglycemia (4); Chronic diarrhea (3); diarrheal disease (3); hyperaldosteronism (3); Hyponatremia (3); kidney damage (3); kidney diseases (3); lung disease (3); type 2 diabetes (3); Ureteral obstruction (3); viral infections (3); bacterial infections (2); blood pressure (2); colorectal cancer (2); Crohn disease (2); cyst (2); cystic kidneys (2); cystinosis (2); distal colitis (2); glomerulosclerosis (2); heart attack (2); Hypercalciuria (2); Hyperkalemia (2).
A further 70 diseases each share a sentence with SLC9A3 in 2 papers or fewer.